ODAD3 (outer dynein arm docking complex subunit 3)
Description:
Component of the outer dynein arm-docking complex (ODA-DC) that mediates outer dynein arms (ODA) binding onto the doublet microtubule. Involved in mediating assembly of both ODAs and their axonemal docking complex onto ciliary microtubules.
Synonyms: CCDC151; MGC20983; ODA10; CILD30
Tractability: Small molecule: a structure with a bound ligand is known. Antibody: its Gene Ontology location is reachable by antibodies, with medium confidence. PROTAC: ubiquitination databases record sites on it.
Gene: Protein-coding gene on chromosome 19 (11,420,604 to 11,435,782, reverse strand). Ensembl gene ENSG00000198003.
Subcellular location: Cytoplasm, cytoskeleton, cilium basal body; Cytoplasm, cytoskeleton, microtubule organizing center, centrosome, centriole; Cytoplasm, cytoskeleton, cilium axoneme
Subcellular location (Human Protein Atlas): Principal piece
Gene Ontology:
Molecular function: protein binding
Biological process: cilium movement; determination of left/right symmetry; outer dynein arm assembly; flagellated sperm motility; regulation of cilium assembly
Cellular component: axoneme; centriole; ciliary basal body; ciliary rootlet; ciliary tip; cilium; outer dynein arm docking complex; sperm flagellum
Genetic constraint (gnomAD): Loss-of-function variants: 57 observed, 69.75 expected, observed/expected ratio (o/e) 0.82, 90% interval 0.66 to 1.02. The upper end of that interval is the gene's LOEUF score, 1.02, which puts it in group 4 of 6, group 1 being the genes least tolerant of losing a copy. Missense variants: 797 observed, 772.88 expected, observed/expected ratio (o/e) 1.03, 90% interval 0.97 to 1.09. Synonymous variants: 327 observed, 318.59 expected, observed/expected ratio (o/e) 1.03, 90% interval 0.94 to 1.12.
Gene-disease validity (ClinGen):
ClinGen rates the evidence that ODAD3 causes each of these diseases.
primary ciliary dyskinesia 30 (autosomal recessive): Definitive.
Homologues: Orthologues: chimpanzee ODAD3 (94% identical), macaque ODAD3 (90% identical), pig ODAD3 (76% identical), dog ODAD3 (74% identical), guinea pig ODAD3 (69% identical), rat Odad3 (66% identical), mouse Odad3 (66% identical), tropical clawed frog odad3 (39% identical), zebrafish odad3 (33% identical), Drosophila melanogaster CG42488 (2% identical). Paralogues in human: ODAD1 (15% identical), CCDC63 (13% identical), TMEM141 (4% identical).
Diseases named in the same sentence as ODAD3 in open-access papers:
ODAD3 is named in the same sentence as 18 diseases in open-access papers, as found by Europe PMC text mining. Sharing a sentence is not in itself a finding about the gene and the disease. The quoted sentences say what the papers report.
primary ciliary dyskinesia (8 papers, 2014 to 2024). A rare, genetically heterogeneous, primarily respiratory disorder characterized by chronic upper and lower respiratory tract disease. "Odad3 gene loss-of-function mutation leads to Primary Ciliary Dyskinesia (PCD), a disease caused by motile cilia dysfunction." (PMID 38920681, 2024).
Hydrocephalus (4 papers, 2019 to 2024). Hydrocephalus is an active distension of the ventricular system of the brain resulting from inadequate passage of CSF from its point of production within the cerebral ventricles to its point of absorption into the systemic circulation. "The majority of Odad3 knockout animals die before sexual maturation due to severe hydrocephalus and failure to thrive, which precludes fertility studies." (PMID 38920681, 2024). "Previously, we demonstrated that Odad3 homozygous knockout mice die before reaching sexual maturity, exhibiting severe hydrocephalus and growth delay." (PMID 38920681, 2024). "Previously, we demonstrated that knockout of the Odad3 gene in mice replicates several features of PCD, such as hydrocephalus, defects in left–right body symmetry, and male infertility, with a complete absence of sperm in the reproductive tract." (PMID 38920681, 2024).
male infertility (3 papers, 2019 to 2025). The inability of the male to effect fertilization of an ovum after a specified period of unprotected intercourse. "The results also highlight the critical role of the Odad3 gene in PCD-related male infertility, suggesting the need for genetic counseling of PCD patients with Odad3 loss-of-function mutations for future practices." (PMID 38920681, 2024). "Here, we studied the role of the Odad3 gene in male infertility using Odad3 mutant mouse models." (PMID 38920681, 2024).
ciliopathy (2 papers, 2025). A genetic disorder of the cellular cilia or the cilia anchoring structures, the basal bodies, or of ciliary function. "However, many ODAD3 variants of uncertain significance (VUS) are associated with ciliopathy in the human genetic database ClinVar." (PMID 40631331, 2025). "Human LRRC56, ODAD3, and ODAD1 models were also generated and show similar structures/folding as well as localization of ciliopathy associated alleles." (PMID 40631331, 2025). "The ciliopathy-associated alleles L136P and L161P mapped to the core LRR domain of Lrrc56, positioned immediately adjacent to the predicted Odad3 interaction surface." (PMID 40631331, 2025). "Human LRRC56, ODAD3 and ODAD1 models were also generated and showed similar structures/folding, as well as localization of ciliopathy-associated alleles." (PMID 41229303, 2025). "Importantly, mutations in ODAD3 and ODAD1 in humans are associated with motile ciliopathies, including PCD." (PMID 40631331, 2025).
oligoasthenoteratozoospermia (1 paper, 2024). A form of male infertility that is characterized by a combination of low number or oligozoospermia, poor motility or asthenozoospermia, and abnormal shape or teratozoospermia of sperms. "Our data showed that even partial ablation of the Odad3 gene in adult testes results in low motile sperm counts, abnormal sperm motility and morphology, conditions defined as oligoasthenoteratozoospermia (OATS)." (PMID 38920681, 2024).
ODAD3 also shares sentences with these, for which no sentence is quoted: Infertility (3 papers); asthenozoospermia (2); Kartagener Syndrome (2); cancer (1); communicating hydrocephalus (1); congenital hydrocephalus (1); Dextrocardia (1); Failure to thrive (1); Kidney Cyst (1); Neonatal respiratory distress (1); polycystic kidney disease (1); prion disease (1); situs inversus (1).